JAK2 (Janus kinase 2)
Diseases named in the same sentence as JAK2 in open-access papers (continued):
Sharing a sentence is not in itself a finding about the gene and the disease.
benign prostatic hyperplasia (2 papers, 2021 to 2025). A non-cancerous nodular enlargement of the prostate gland. "Therefore, this study conducted a pharmacodynamic evaluation of rape pollen maca chewable tablets on benign prostatic hyperplasia, investigated their impact on gut microbiota, and further explored the IL-6/JAK2/STAT3 signaling pathway in prostatic tissues." (PMID 41472815, 2025).
breast adenocarcinoma (2 papers, 2016 to 2025). "Administration of anti-Epo-antibody, soluble EpoR or an inhibitor of JAK2 resulted in a delay in tumor growth in a experimental model with rat mammary adenocarcinoma cells." (PMID 26919105, 2016).
Chronic colitis (2 papers, 2015 to 2025). A chronic inflammatory disease of the large intestine (colon, cecum and rectum). "We provided compelling evidence that the novel synthetic neuroactive peptide SVHRSP alleviates DSS-induced chronic colitis via the α7nAChR-mediated JAK2/STAT3 signaling pathway." (PMID 41300453, 2025). "Differently, JAK2 phosphorylation was reduced by the combined treatment but not by 5-ASA alone, suggesting that inhibition of the JAK/STAT pathway is likely to participate in the effect of 5-ASA plus berberine against chronic colitis." (PMID 26642326, 2015).
chronic leukemia (2 papers, 2015 to 2019). A slowly progressing leukemia characterized by a clonal (malignant) proliferation of maturing and mature myeloid cells or mature lymphocytes. "In fact, JAK2 translocations have been described in acute and chronic leukemias of myeloid and lymphoid phenotypes." (PMID 25789185, 2015). "JAK2 fusions are reported in acute and chronic leukemias of myeloid and lymphoid phenotypes." (PMID 25789185, 2015).
chronic rhinosinusitis (2 papers, 2021 to 2023). Chronic form of sinusitis. "This study investigates the association of p-JAK2 and JAK2-associated cytokines from nasal polyp (NP) tissue with disease severity, and evaluates the p-JAK2-mediated STATs in chronic rhinosinusitis (CRS) with NP." (PMID 34356683, 2021). "In this study, we tested the SpA expression in S. aureus from chronic rhinosinusitis patients and investigated the effects of SpA on HNECs inflammation through Interferon Gamma Receptor 1(IFNGR1)/phosphorylated Janus Kinase 2 (p-JAK2) pathway." (PMID 36527461, 2023).
coccidioidomycosis (2 papers, 2024 to 2025). A fungal infection caused by Coccidioides immitis. "This case report explores the consequences of inhibiting JAK1 and JAK2 via ruxolitinib, particularly in the context of fungal defense in a patient diagnosed with pulmonary coccidioidomycosis." (PMID 41164159, 2025). "In a recent case series of 135 patients receiving ruxolitinib (JAK1/JAK2 inhibitor), 8 developed symptomatic coccidioidomycosis; 4 had coccidioidomycosis preceding ruxolitinib, and each had primary pulmonary disease while on therapy." (PMID 38667927, 2024).
cognitive decline (2 papers, 2020 to 2022). "In summary, this study demonstrated that prolonged aerobic exercise can reverse the cognitive decline caused by T2DM, which may be related to the activity of AMPK/SIRT1 and the inhibition of JAK2/STAT3 signalling in T2DM mice." (PMID 35578689, 2022). "Aerobic exercise may also be used to prevent synapse formation disorders and cognitive decline through enhancing the AMPK/SIRT1 and inhibiting the JAK2/STAT3." (PMID 35578689, 2022).
colorectal tumor (2 papers, 2022 to 2025). "JAK2 inhibitor CEP-33779 inhibited colorectal tumor growth by inhibiting IL-6/JAK2/STAT3 signal transduction." (PMID 36591515, 2022). "It inhibits colorectal tumor growth by inhibiting IL-6/JAK2/STAT signal transduction." (PMID 36591515, 2022).
diabetic neuropathy (2 papers, 2019 to 2021). A chronic, pathological complication associated with diabetes mellitus, where nerve damages are incurred due to diabetic microvascular injury involving small blood vessels that supply these nerves, resulting in peripheral and/or autonomic nerve dysfunction. "The aim of the present study was to further elucidate the role of JAK2/STAT3-CAV-1-NR2B on painful diabetic neuropathy." (PMID 30830585, 2019).
disc degeneration (2 papers, 2024 to 2025). "For example, one study demonstrated that leptin promotes catabolic activity in rat NPCs by upregulating the expression of MMP‐1, MMP‐13, ADAMTS4, and ADAMTS5 via activation of the JAK2/STAT3 pathway, suggesting a mechanism contributing to disc degeneration." (PMID 41497807, 2025). "Subsequent downregulation of LTF led to increased phosphorylation of JAK2 and STAT3, culminating in enhanced CEP calcification, senescence and ECM degradation, thereby contributing to disc degeneration." (PMID 39392081, 2024). "The findings showed that both JAK2 silencing and JAK inhibitor treatment effectively reduced SASP expression in senescent NPCs, underscoring the pivotal role of the JAK2/STAT3 signaling pathway in SASP regulation and highlighting its therapeutic potential in mitigating disc degeneration." (PMID 41497807, 2025).
eczema (2 papers, 2018 to 2025). "In contrast to the model group, SYXL (300, 900 μg/mL) inhibited the phosphorylation of JAK2 and STAT3, suggesting that suppression of JAK/STAT pathway activation may represent a key mechanism underlying SYXL’s anti-inflammatory and anti-eczema properties." (PMID 40612058, 2025). "ELISA and Western blotting analyses revealed that SYXL alleviated eczema-like skin lesions induced by DNCB in animal models, reversed histopathological abnormalities, curbed the expression of pro-inflammatory cytokines IL-1β, IL-6, and TNF-α, and inhibited the phosphorylation of JAK2 and STAT3." (PMID 40612058, 2025).
emphysema (2 papers, 2025). "In alignment with these observations, our findings identified an upregulation of RAGE and STAT1 genes in lung tissue, alongside increased expression levels of RAGE, p-JAK2, p-STAT1, p-STAT3 and p-STAT5 in pulmonary mDCs in a smoking-induced mouse model of emphysema." (PMID 40951546, 2025). "administration of AG490 (JAK2 inhibitor) or HJC0152 (STAT3 inhibitor) significantly reduced both the frequency and absolute cell number of Siglec-F+ neutrophils in the lungs of PPE-treated mice, and this reduction was accompanied by marked alleviation of emphysema symptoms, as assessed by MLI." (PMID 40461699, 2025).
Encephalopathy (2 papers, 2015 to 2019). Encephalopathy is a term that means brain disease, damage, or malfunction. "Although clinical development of fedratinib was discontinued in November 2013 (due to a few reports of treatment-emergent encephalopathy, resembling Wernicke’s), the effects of JAK2 inhibition on BMF may be relevant for predicting the long-term efficacy of other JAK2 inhibitors." (PMID 26357842, 2015).
erectile dysfunction (2 papers, 2023 to 2024). Persistent or recurrent inability to achieve or to maintain an erection during sexual activity. "Genetically predicted JAK2 was causally associated with erectile dysfunction in inverse variance weighting (OR = 1.109, 95% CI = 1.029–1.196, p = 0.007) and weighted median method (OR = 1.117, 95% CI = 1.003-1.245, p = 0.044)." (PMID 37407943, 2023). "Here we investigated the causal relationship between JAK2 and erectile dysfunction." (PMID 37407943, 2023). "Although these are pilot studies based on erectile dysfunction in diabetic mice, there is still reason to believe that a corresponding pathological impairing effect on ED in JAK2-mediated oxidative stress exists." (PMID 37407943, 2023). "However, the causal relationship between JAK2 and erectile dysfunction remains unclear." (PMID 37407943, 2023). "Several observational studies have reported the role of JAK2 in erectile dysfunction." (PMID 37407943, 2023).
Fanconi Anaemia (2 papers, 2021 to 2022). "These include variants in genes encoding FANCE, a subunit of the Fanconi Anaemia (FA) nuclear complex; NKX2-1, a transcription factor and negative regulator of the NF-κB signalling pathway; and other recognized oncogenes JAK2, PRDM16, BMPR1A and tumor-suppressor genes KMT2C, FAT4, and LRP1B." (PMID 35954343, 2022).
gastritis (2 papers, 2019 to 2024). Inflammation of the stomach. "Interestingly, EtOH/HCl-induced gastritis mouse models demonstrated an increase in IL-1β, iNOS, TNF-α, INF-β, and COX-2 gene expression and an increase in phosphorylation of p65, Syk, and JAK2." (PMID 31929819, 2019). "Apart from these genes, targets like CCL2, IL6, JAK2, IL2RA and CXCR1 were also of vital importance in the Hot herbs’ targets network, which might infer us that another potential mechanism of Hot herbs against Cold ZEHNG gastritis was to regulate immune responses." (PMID 39367502, 2024).
glaucoma (2 papers, 2021 to 2025). Increased pressure in the eyeball due to obstruction of the outflow of aqueous humor. "This current study reveals a novel mechanism by which baicalin regulates the microglial-ferroptosis interplay through the JAK2/STAT3 pathway in a glaucoma model." (PMID 41208867, 2025). "TRPV4 activation induces Müller cell gliosis and TNF-α elevation via the JAK2/STAT3/NF-κB pathway, which may exacerbate RGC apoptosis in glaucoma; these results suggest that TRPV4 can serve as a therapeutic target in glaucoma treatment." (PMID 34789280, 2021). "In addition, TRPV4 activation could enhance the release of inflammatory cytokines (e.g., tumor necrosis factor-α [TNF-α]) through JAK2/STAT3/NF-kB signaling pathways in Müller cells and elevated expression of TNF receptor 1 in RGCs; this process is involved in RGC apoptosis during glaucoma." (PMID 34789280, 2021).
Headache (2 papers, 2022). Cephalgia, or pain sensed in various parts of the head, not confined to the area of distribution of any nerve. "Multiple logistic regression analysis showed that younger age, but not platelet counts or the JAK2 V617F mutation, was independently associated with headaches (Odds Ratios 2.004, 95% confidence intervals 1.293–3.108, P = 0.002)." (PMID 36561301, 2022). "A statistically significant difference was found only in the headaches and ICH presentation in the JAK-2 group and headache presentation in the APLA group." (PMID 35493844, 2022).
hemorrhagic stroke (2 papers, 2022). A stroke caused by a bleed on the brain. "Herein, we present a case of JAK2 gene mutation-associated ET in a patient who developed both ischemic and hemorrhagic stroke, and discuss potential underlying mechanisms." (PMID 36397023, 2022). "We present a case of JAK2 gene mutation-associated ET in a patient who developed both ischemic and hemorrhagic stroke." (PMID 36397023, 2022).
histoplasmosis (2 papers, 2024 to 2025). A disease caused by the fungus Histoplasma capsulatum. "The histoplasmosis is completely resolved with a proper antifungal treatment course and switching treatment to the selective JAK2 inhibitor fedratinib." (PMID 41164159, 2025). "Later, the patient received fedratinib, a relatively JAK2-selective inhibitor, without relapse of histoplasmosis." (PMID 38667935, 2024).
Hypercholesterolemia (2 papers, 2020 to 2022). An increased concentration of cholesterol in the blood. "While JAK2 inhibition ameliorates MPN phenotypes driven by JAK2 or related gene mutations in both mouse models and humans, its impact on excessive myelopoiesis and atherogenesis caused by hypercholesterolemia and defective cholesterol efflux from HSPCs and myeloid progenitors is unknown." (PMID 32086626, 2020).
hyperprolactinemia (2 papers, 2018 to 2021). Abnormally high level of prolactin in the blood. "Many antipsychotics cause serum hyperprolactinemia as an adverse side effect; prolactin-Janus kinase 2 (JAK2)-signal transducer and activator of transcription 5 (STAT5) signaling both induces cell differentiation and suppresses apoptosis." (PMID 29778097, 2018).
inflammatory bone disease (2 papers, 2017 to 2023). "The JAK2/STAT3 signal transduction pathway is one of the main pathways through which IL-6 exerts its biological roles and plays a critical part in inflammatory bone disease." (PMID 36643585, 2023).
ischemic disease (2 papers, 2013 to 2021). Lack of blood supply to an area of the body, resulting in impairment of tissue oxygenation. "Our study indicated that AS-IV is a key regulator of NO and angiogenesis through the JAK2/STAT3 and ERK1/2 pathways, which provides a mechanistic basis for the potential use of this compound in the treatment of clinical ischemic diseases." (PMID 24135938, 2013).
kidney inflammation (2 papers, 2022 to 2025). "Accumulating evidence suggests that the limitation of the NLRP3 inflammasome and JAK2/STAT3 signaling contributes to attenuate kidney inflammation." (PMID 41278550, 2025).
kidney injury (2 papers, 2019 to 2022). Trauma to the kidney. "In summary, our data suggest that proteolytic processing of IL‐6 by meprin β plays an important role in modulating IL‐6 expression and influences the downstream signal transduction/pathway mediated via JAK2/STAT3 in IR‐induced kidney injury." (PMID 36117389, 2022). "The data provide evidence for meprin β modulation of IL‐6/JAK2/STAT3 signaling and their convergence to activate the downstream target genes of IL‐6 signaling in IR‐induced kidney injury." (PMID 36117389, 2022).
leukoerythroblastosis (2 papers, 2013 to 2025). "However, the presence of leukoerythroblastosis, a hypercellular bone marrow with reticulin fibrosis, the myeloid hyperplasia, and the megakaryocytic morphology as well as the absence of the JAK2 mutation did not favor a diagnosis of ET." (PMID 23781354, 2013).
lupus nephritis (2 papers, 2021 to 2022). Glomerulonephritis in the context of systemic lupus erythematosus. "In addition, inhibition of the JAK2/STAT1 pathway in lupus nephritis mice can alleviate renal function damage and immune complex deposition and reduce the level of proteinuria and anti‐dsDNA IgG." (PMID 35875970, 2022). "Artesunate reportedly attenuated STAT1 phosphorylation in cultured HUVECs stimulated with IFNα and suppressed phosphorylation of JAK2 and STAT3 in the kidney of MRL/lpr mice, resulting in an amelioration of the symptoms of lupus nephritis." (PMID 34567013, 2021).
lymphoproliferative disorders (2 papers, 2014 to 2020). "The JAK2 V617F allele has rarely been evaluated in lymphoproliferative disorders." (PMID 25013507, 2014).
medulloblastoma (2 papers, 2017 to 2021). A malignant, invasive embryonal neoplasm arising from the cerebellum. "Inhibiting Jak2 reduced the levels of Atoh1 in medulloblastoma cells and slowed tumor growth in mice." (PMID 29168692, 2017). "Taken together, inhibiting Jak2-mediated tyrosine 78 phosphorylation could provide a viable therapy for medulloblastoma." (PMID 29168692, 2017). "We discovered tyrosine 78 of Atoh1 is phosphorylated by a Jak2-mediated pathway only in tumor-initiating cells and in human SHH-type medulloblastoma." (PMID 29168692, 2017).
metastatic disease (2 papers, 2021 to 2024). "Consistent with the ALK staining, p-JAK2 was present only in the metastasis of these three cases, and p-STAT6 staining did not appear in any metastatic tumors." (PMID 34090412, 2021).
obstructive sleep apnea (2 papers, 2022 to 2023). "Other targeted pathways reported for the effects of A. graveolens in neurological disorders include Nrf2 and NF-κB pathways; BDNF/ERK/mTOR (antidepressant); CNTF/CNTFRa/JAK2/STAT3 (cerebral blood flow decreases); and SIRT1/PGC-1a (obstructive sleep apnea)." (PMID 37570794, 2023).
osteosclerosis (2 papers, 2015 to 2022). Abnormally high bone density. "Overall, this study underlines that JAK2 inhibition, using a JAK2-selective inhibitor, may lead to different effects on fibrosis, osteosclerosis, granulocytosis, erythropoiesis or platelet counts according to MPN disease stage." (PMID 26176817, 2015). "These accumulating data that reinforce our results strongly suggest that correction of BM fibrosis and osteosclerosis development in early MPN phase is strictly mediated through inhibition of JAK2." (PMID 26176817, 2015). "Strikingly, complete blockade of fibrosis and osteosclerosis was observed in the PPMF model, linked to correction of MK hyper/dysplasia, but not in the PTMF model, suggesting that MF development may also become JAK2-independent." (PMID 26176817, 2015).
peripheral T-cell lymphoma (2 papers, 2017 to 2022). "This concept is supported by the recent report of 6 cases of a variety of JAK2 rearrangements with peripheral T-cell lymphoma, one of which harbored the PCM1-JAK2 fusion." (PMID 35472244, 2022).
peritonitis (2 papers, 2016 to 2025). Inflammation of the peritoneum (tissue that lines the abdominal wall and covers most of the organs in the abdomen). "Moreover, the increase in p-Jak2 was restricted to macrophages but not to neutrophils during acute peritonitis." (PMID 27397585, 2016).
polycystic kidneys (2 papers, 2019 to 2021). "In summary, we show that JAK2 is highly expressed in polycystic kidneys and its blockade reduces cystic growth." (PMID 30872773, 2019).
prostate adenocarcinoma (2 papers, 2019 to 2020). "This suggestion is reinforced by the fact that the expression of LEP, leptin receptor (LEPR) and its main downstream signaling genes (JAK2, STAT3) is reduced in prostate adenocarcinoma, suggesting that this system is involved in the mechanism of apoptosis defense in proliferating tumor cells." (PMID 31671654, 2019).
respiratory failure (2 papers, 2024). The significant impairment of gas exchange within the lungs resulting in hypoxia, hypercarbia, or both, to the extent that organ tissue perfusion is severely compromised. "By inhibiting the JAK1 and JAK2 pathways, it can block the immune cascade and reduce viral replication, which is beneficial for reducing respiratory failure and mechanical ventilation." (PMID 38378889, 2024). "Corticosteroids, tocilizumab, and/or JAK2 inhibitors were added in cases of progressive respiratory failure and increased inflammatory parameters." (PMID 39031740, 2024).
retinal degeneration (2 papers, 2013 to 2019). Degeneration of the retina. "Our results demonstrate that during RCS rats’ retinal degeneration, classically activated immune cells up-regulated JAK2/STAT3 pathway and produce persistent pro-inflammatory factors, but only transient anti-inflammatory factors in early stage." (PMID 31402855, 2019). "LIF signaling during retinal degeneration is thought to act through the JAK/STAT pathway including activation of Janus activated kinase 2 (JAK2), JAK3 and signal transducers and activators of transcription 3 (STAT3)." (PMID 23372671, 2013). "In our research, in vivo experiments demonstrated that the JAK2/STAT3 pathway became activated during degenerative period which was the same as research on retinal degeneration has shown that JAK2 and STAT3 proteins are involved in photoreceptor apoptosis, especially in rd1 mice model." (PMID 31402855, 2019). "As during retinal degeneration, the apoptosis of photoreceptors and glia cell produce a large number of IL-6, which band to gp130, and form a complex to activate the kinase function of JAK2." (PMID 31402855, 2019).
retinal ischemia (2 papers, 2025). A ischemic disease that involves the retina. "JAK2's role in ocular microvascular damage primarily involves its participation in the JAK-STAT signaling pathway, which promotes retinal ischemia-reperfusion injury." (PMID 40391004, 2025).
Right ventricular hypertrophy (2 papers, 2020 to 2021). In this case the right ventricle is more muscular than normal, causing a characteristic boot-shaped (coeur-en-sabot) appearance as seen on anterior- posterior chest x-rays. "Therefore, induction of Jak2 deficiency in SMCs protected mice from hypoxia‐induced increase of right ventricular systolic pressure (RVSP), right ventricular hypertrophy and pulmonary vascular remodelling." (PMID 31943454, 2020).